USP47 (ubiquitin specific peptidase 47)
Description:
Ubiquitin-specific protease that specifically deubiquitinates monoubiquitinated DNA polymerase beta (POLB), stabilizing POLB thereby playing a role in base-excision repair (BER). Acts as a regulator of cell growth and genome integrity. May also indirectly regulate CDC25A expression at a transcriptional level.
Synonyms: TRFP
Tractability: Small molecule: a high-quality ligand is known; it belongs to a druggable protein family. PROTAC: ubiquitination databases record sites on it; its protein half-life has been measured; a small molecule that binds it is known.
Target class: Cysteine protease; Cysteine protease CA clan; Protease; Enzyme; Cysteine protease C19 family
Gene: Protein-coding gene on chromosome 11 (11,841,423 to 11,961,887, forward strand). Ensembl gene ENSG00000170242.
Subcellular location: Cytoplasm
Subcellular location (Human Protein Atlas): Intermediate filaments; Vesicles
Pathways (Reactome):
Metabolism of proteins: Ub-specific processing proteases
Gene Ontology:
Molecular function: cysteine-type deubiquitinase activity; deubiquitinase activity; protein binding; WD40-repeat domain binding
Biological process: base-excision repair; DNA damage response; monoubiquitinated protein deubiquitination; positive regulation of canonical Wnt signaling pathway; protein deubiquitination
Cellular component: cytoplasm; nucleus; SCF ubiquitin ligase complex; nucleoplasm
Genetic constraint (gnomAD): Loss-of-function variants: 29 observed, 124.26 expected, observed/expected ratio (o/e) 0.23, 90% interval 0.17 to 0.32. The upper end of that interval is the gene's LOEUF score, 0.32, which puts it in group 1 of 6, group 1 being the genes least tolerant of losing a copy. Missense variants: 1,152 observed, 1,441 expected, observed/expected ratio (o/e) 0.8, 90% interval 0.76 to 0.84. Synonymous variants: 479 observed, 491.03 expected, observed/expected ratio (o/e) 0.98, 90% interval 0.9 to 1.05.
Homologues: Orthologues: chimpanzee USP47 (99% identical), macaque USP47 (99% identical), pig USP47 (98% identical), rabbit USP47 (98% identical), guinea pig USP47 (97% identical), rat Usp47 (96% identical), mouse Usp47 (95% identical), dog USP47 (91% identical), tropical clawed frog usp47 (82% identical), zebrafish usp47 (82% identical), Drosophila melanogaster Usp47 (35% identical), Caenorhabditis elegans T05H10.1 (30% identical). Paralogues in human: USP40 (19% identical), USP34 (12% identical), USP9X (11% identical), USP9Y (11% identical), USP42 (11% identical), USP24 (11% identical), USP36 (10% identical), USP48 (10% identical), USP7 (10% identical), USP38 (10% identical), USP31 (9% identical), USP15 (9% identical), and 59 more.
Diseases named in the same sentence as USP47 in open-access papers:
USP47 is named in the same sentence as 44 diseases in open-access papers, as found by Europe PMC text mining. Sharing a sentence is not in itself a finding about the gene and the disease. The quoted sentences say what the papers report.
gastric cancer (12 papers, 2017 to 2025). A primary or metastatic malignant neoplasm involving the stomach. "USP47 regulates gastric cancer cell viability and chemoresistance by activating the NF-κB signaling pathway." (PMID 39605891, 2024). "USP47 positively correlated with the tumor-infiltrating Treg signature in samples from patients with colorectal cancer and gastric cancer." (PMID 37788092, 2023). "USP47 plays an important role in cancers such as gastric cancer, medulloblastoma, and colorectal cancer; however, its role in CML remains unexplored." (PMID 33397955, 2021). "Ubiquitin-specific peptidase 47 also participated in the regulation of cell viability and chemotherapeutic resistance in gastric cancer cells." (PMID 34604226, 2021). "Similar to AGS cells, knockdown of USP47 in gastric cancer cell line (NCI-N87) constitutively decreased βTrCP levels, and reduced nuclear translocation of RelA." (PMID 29786670, 2018). "In this study, we addressed the molecular details of NF-κB regulation using USP47, and examined the viability of USP47 as a promising target for drug intervention to enhance the action of current drugs, and to overcome chemoresistance in gastric cancer cells." (PMID 29786670, 2018). "Our results show that depletion of USP47 in AGS gastric cancer cells results in decreased protein levels of phospho-RelA and β-transducin repeat-containing protein (βTrCP)." (PMID 29786670, 2018). "As one such target, we identified the ubiquitin specific protease 47 (USP47), that was previously shown to be essential for the proliferation of gastric carcinomas." (PMID 29786670, 2018). "Previous studies showed that miR-204 suppressed gastric cancer through targeting USP47, RAB22A, SIRT1, Snai1, and so forth." (PMID 28133610, 2017). "Furthermore, it has been reported that miR-204-5p reduces USP47 levels by directly targeting it and inhibiting cell proliferation in gastric cancer." (PMID 35205710, 2022). "Because CPT and Eto are known to promote NF-κB-dependent apoptosis resistance, USP47 inhibition may be a suitable strategy to overcome drug resistance induces by NF-κB signaling pathway in gastric cancer." (PMID 34604226, 2021). "USP47 is the target protein of miR-204-5p, and high miR-204-5p expression leads to down-regulation of USP47 expression, thereby inhibiting proliferation of gastric cancer and ovarian cancer cells." (PMID 34604226, 2021). "USP47 was found as a target of miRNA-204-5p and involves in gastric cancer cell proliferation." (PMID 30718521, 2019). "Inhibition of USP47 might be a suitable strategy to downregulate NF-κB activity, and to overcome chemoresistance in gastric cancer." (PMID 29786670, 2018). "Gastric cancer patients have low cure rates after chemotherapy; we therefore asked whether USP47 knockdown could enhance apoptosis in gastric cancer cells when treated with chemotherapeutic drugs." (PMID 29786670, 2018). "Apart from its regulatory role in the NF-κB pathway, USP47 constitutes an interesting target for gastric cancer chemotherapy, because it promotes gastric carcinoma cell proliferation, and its depletion sensitize cancer cells to chemotherapy, probably due to the upregulation of Cdc25a." (PMID 29786670, 2018). "We therefore addressed the question of whether USP47 inhibition could affect cell survival/proliferation of gastric cancer cells." (PMID 29786670, 2018). "Inhibition of USP47 activity could represent a viable strategy for gastric cancer chemotherapy by downregulating transcription of NF-κB-regulated pro-survival genes, and overcoming NF-κB-dependent chemoresistance." (PMID 29786670, 2018). "Therefore, targeting of USP47 represents a suitable strategy to overcome drug resistance in gastric carcinomas." (PMID 29786670, 2018). "This together with its potential to overcome chemoresistance in gastric carcinoma cells suggests that USP47 could represent a promising therapeutic target structure." (PMID 29786670, 2018).
gastric cancer (continued). "Getting together, in miR-204 regulation pathway, USP47, RAB22A, SIRT1, Snai1, and so forth and SOX4 may play an associating role contributing to gastric cancer progressing." (PMID 28133610, 2017). "By analyzing genomic data from a gastric cancer (GC) case-control study (2,117 individuals), focusing on the ubiquitin-specific protease (USP) family, we identify the SNP rs72856331 (G>A) in the promoter region of the proto-oncogene USP47 as a putative susceptibility allele for GC." (PMID 39998882, 2025). "Furthermore, after knockdown of USP47 by RNA interference, we analyzed in gastric cancer cell lines metabolic activity/viability in an MTT assay, and apoptotic cell death by Annexin V staining and poly(ADP-Ribose) polymerase (PARP)-1, caspase 3, and caspase 8 cleavage, respectively." (PMID 29786670, 2018). "USP47 was positively correlated with the tumor-infiltrating Treg signature in samples from patients with colorectal cancer (CRC) and gastric cancer (GC)." (PMID 37788092, 2023). "Ubiquitin-specific peptidase 47 plays a role in various cancers, including colorectal cancer (CRC), breast cancer, lung cancer, and gastric cancer." (PMID 34604226, 2021). "Based on the observation that USP47 promotes the proliferation of gastric carcinomas, we performed a USP47 knockdown in AGS gastric carcinoma cells." (PMID 29786670, 2018). "We found that USP47 contributes to cell viability and chemoresistance in NCI-N87 gastric carcinoma cells treated with etoposide and camptothecin." (PMID 29786670, 2018). "USP47, RAB22A, SIRT1, Snai1, and so forth are targets of miR-204 that mediate miR-204 reducing the oncogenicity of gastric cancer." (PMID 28133610, 2017). "Furthermore, another study indicated that miR-204-5p suppressed gastric cancer cell growth by inhibiting RAB22A and USP47." (PMID 33888645, 2021). "Interestingly, in the CPT- and Eto-resistant gastric carcinoma cell line NCI-N87 USP47 depletion resulted in pronounced apoptosis induction after CPT and Eto treatment." (PMID 29786670, 2018). "In addition, USP47 contributes to chemoresistance and viability in NCI-N87 gastric carcinoma cells." (PMID 29786670, 2018). "Second, USP47 is highly expressed in several types of BCR-ABL-negative cell lines, including colorectal cancer cells and gastric cancer cells." (PMID 33397955, 2021). "Even though USP47 depletion failed to increase apoptotic cell death in AGS cells treated with camptothecin (CPT) and etoposide (Eto), it overcame chemoresistance in NCI-N87 gastric carcinoma cells." (PMID 29786670, 2018).
colorectal cancer (8 papers, 2020 to 2023). A primary or metastatic malignant neoplasm that affects the colon or rectum. "USP47 is a direct target of miR-188-50, and the overexpression of USP47 attenuated LINC00669 knockdown-induced tumor-suppressive effects in colorectal cancer cells." (PMID 37740002, 2023). "USP47 functions as a DUB for YAP in colorectal cancer, USP47 elevation leads to the stabilization of YAP and promotes colorectal cancer cell proliferation." (PMID 37349820, 2023). "USP47 functions as a DUB for YAP in colorectal cancer, USP47 elevation leads to stabilization of YAP and promotes colorectal cancer cell proliferation." (PMID 33613102, 2021). "The decreased level of USP47 in colorectal cancer was also evident when examined by immunohistochemistry." (PMID 34630087, 2021). "In the present study, we found that the deubiquitinating enzyme USP47 was markedly decreased in primary colorectal cancers (CRC)." (PMID 34630087, 2021). "As found in primary CRCs, some colorectal cancer cell lines expressed detectable USP47." (PMID 34630087, 2021).
colon cancer (7 papers, 2017 to 2025). "Based on the gain- and loss-of-function approaches, the cellular functions of colon cancer cells by the E2F7-regulated miR-199b/USP47/MAPK axis were assessed." (PMID 33489876, 2020). "The deficiency of USP47 impaired the transcriptional activity of SATB1 target genes and inhibited cell proliferation, migration, and tumorigenesis in a mouse model of colon cancer." (PMID 34604226, 2021). "All in all, the results of this study revealed that E2F7 inhibited miR-199b to enhance the development of colon cancer by targeting USP47." (PMID 33489876, 2020). "For instance, E2F7 binds the putative promoter region of the miR‐199b gene and significantly repressed the expression of this tumor‐suppressing miRNA in colon cancer, which leads to the increase in its target USP47, and sequentially enhances the MAPK signaling pathway and facilitates tumor progress." (PMID 35924788, 2022). "Thus, we conducted investigation on the correlation among E2F7, miR-199b, and USP47 and their effects on colon cancer stem cell activity." (PMID 33489876, 2020). "However, the relationship among E2F7, miR-199b, and USP47 in colon cancer is scantly reported in the literature." (PMID 33489876, 2020). "The expression of USP47 in colon cancer tissues from the GEPIA2 database showed a downward trend." (PMID 33489876, 2020). "Notably, USP47 was found to be overexpressed in human CRC tissues as well as colon cancer cell lines." (PMID 29162839, 2017). "Besides, it has been well-documented that the USP47 deubiquitin-modified mitogen-activated protein kinase (MAPK) axis could stabilize MAPK that participates in the regulation of colon cancer metastasis." (PMID 33489876, 2020). "Given that USP47 correlated with the Treg signature in human CRC and GC tissues, we inoculated Usp47+/+Foxp3-Cre and Usp47fl/flFoxp3-Cre mice with MC38 murine colon cancer cells to examine the functional importance of USP47 in tumor-infiltrating Tregs." (PMID 37788092, 2023). "Additionally, reversible ubiquitination of SATB1 by USP47 and SMURF2 promotes colon cancer proliferation." (PMID 41208974, 2025). "Therefore, we are convinced that present results show that E2F7 suppressed the miR-199b expression and promoted USP47 to stabilize MAPK proteins, thereby contributing to colon cancer development." (PMID 33489876, 2020). "In conclusion, our study reported that E2F7 downregulated the expression of miR-199b, leading to the upregulation of the miR-199b target USP47 that stabilized MAPK, promoting colon cancer stem cell activity, thereby accelerating the development and progression of colon cancer." (PMID 33489876, 2020).
chronic myelogenous leukemia (5 papers, 2021 to 2024). "Notably, USP47 shows promise as a target for overcoming TKI resistance in chronic myelogenous leukemia (CML) and is implicated in protein aggregation and clearance pathways related to neurodevelopment and neurodegenerative diseases." (PMID 38832955, 2024). "Targeting USP47 is a promising strategy to overcome tyrosine kinase inhibitor resistance and eradicate leukemia stem/progenitor cells in chronic myelogenous leukemia." (PMID 37788092, 2023). "P22077, a dual inhibitor of USP7/USP47, overcomes tyrosine kinase inhibitor resistance and eradicates leukemia stem/progenitor cells in chronic myelogenous leukemia through inhibiting its novel substrate Y-box binding protein 1 (YB-1) deubiquitination and suppresses DNA damage repair." (PMID 35301297, 2022).
leukemia (5 papers, 2021 to 2024). A malignant (clonal) hematologic disorder, involving hematopoietic stem cells and characterized by the presence of primitive or atypical myeloid or lymphoid cells in the bone marrow and the blood. "Targeting USP47 can overcome the resistance to tyrosine kinase inhibitors and eradicate leukemia progenitor cells." (PMID 36483601, 2022). "Consistently, fewer CML leukemia cells were detected in the PB of Usp47−/− group." (PMID 33397955, 2021). "Furthermore, the number of CML leukemia stem/progenitor cells (GFP+ LSK cells) in the Usp47−/− group is significantly decreased compared with the Usp47+/+ group." (PMID 33397955, 2021). "Besides, there is a remarkable decrease in the number of CML leukemia cells in the PB and BM of the Usp47−/− mice." (PMID 33397955, 2021). "Here, the authors show that targeting the ubiquitin peptidase USP47 overcomes TKI resistance and eliminates leukaemia stem/progenitor cells in primary and xenograft CML murine models." (PMID 33397955, 2021). "Specifically, we demonstrate that USP47 is highly expressed in primary CML cells and promotes cell proliferation, while Usp47 knockout significantly prolongs the survival of BCR-ABL and BCR-ABLT315I-induced CML mice by reducing leukemia stem/progenitor cells." (PMID 33397955, 2021). "In summary, we demonstrate that USP47 is a target for CML treatment and targeting USP47 is a promising strategy for overcoming TKI resistance and eradicating leukemia stem/progenitor cells in CML." (PMID 33397955, 2021). "Together, targeting USP47 is a promising strategy to overcome TKI resistance and eradicate leukemia stem/progenitor cells in CML." (PMID 33397955, 2021). "Additionally, USP47 promotes AML cell proliferation, enhances resistance to imatinib, and eliminates leukemia progenitor cells in CML by stabilizing Y-box-binding protein 1 (YBX1), a vital regulator of cell survival observed in multiple solid tumors and CML." (PMID 39048945, 2024). "In addition, substantial infiltration of CML leukemia cells (GFP-positive cells) was detected in the liver and spleen of the Usp47+/+ mice." (PMID 33397955, 2021).
lung carcinoma (3 papers, 2021 to 2026). "We also confirmed that USP47 gene expression was higher in lung cancer tissues through the analysis of microarray data obtained from the National Center for Biotechnology Information’s Gene Expression Omnibus (GEO) database (accession number GSE40275)." (PMID 35205710, 2022). "In particular, a depletion in USP47 reduced tumor growth in xenograft models using A549 lung cancer cells." (PMID 35205710, 2022). "Ubiquitin-specific peptidase 47 knockdown inhibited the proliferation of A549 lung cancer cells and PC3 prostate cancer cells by deubiquitinating β-catenin." (PMID 34604226, 2021). "Multiplex RT-PCR showed distinct mRNA expression profiles of several DUB genes, including USP35, USP36, USP37, USP47, USP49, and OTUD6B in A549 lung cancer cells following exposure to cisplatin." (PMID 41399373, 2026). "Following the observation of altered expression levels of USP35, USP36, USP37, USP47, USP49, and OTUD6B in response to cisplatin treatment in lung cancer cells, both at the mRNA and protein levels, we sought to explore their significance in lung cancer." (PMID 41399373, 2026). "Bioinformatics analysis demonstrates that these DUBs except USP47 are upregulated and overall survival analysis indicates that lower expression of these DUBs, except USP37 and USP49, is correlated with improved overall survival in lung cancer patients." (PMID 41399373, 2026). "From this analysis, we found that the miR-101-3p expression levels were downregulated in both the tissue and plasma of lung cancer patients as opposed to USP47 expression." (PMID 35205710, 2022). "Substantiating these findings, western blotting analysis confirmed the protein expression levels of USP35, USP36, USP37, USP47, USP49, and OTUD6B in cisplatin-treated lung cancer cells, mirroring the mRNA trends observed in non-treated counterparts except for OTUD6B." (PMID 41399373, 2026).
osteosarcoma (3 papers, 2021 to 2022). A usually aggressive malignant bone-forming mesenchymal neoplasm, predominantly affecting adolescents and young adults. "A recently published paper demonstrated that long-non-coding RNA (lncRNA) DSCAM-AS1 play a role as a sponge for miR-101-3p, resulting in the exacerbation of osteosarcoma progression by protecting the miR-101-3p-mediated depletion of USP47." (PMID 35205710, 2022). "Knockdown of USP47 expression in human osteosarcoma U-2OS and SAOS-2 cells and breast cancer T47D, BT-20, and MCF7 cells significantly induced apoptosis and improved the sensitivity to chemotherapeutic drugs." (PMID 34604226, 2021). "In osteosarcoma cells, USP47 is the target gene of miR-101-3p, and lncRNA DSCAM-AS1 controls USP47 expression and regulates osteosarcoma progression by binding to miR-101-3p." (PMID 34604226, 2021).
ovarian carcinoma (3 papers, 2021 to 2025). A malignant neoplasm originating from the surface ovarian epithelium. "Through bioinformatics analysis, we identified the deubiquitinase USP47 as being associated with NAD+ levels and correlated with various anti-tumor genes in ovarian cancer microenvironment T cells." (PMID 40846839, 2025). "MiR-204-5p attenuates cell growth by decreasing USP47 expression in ovarian cancer." (PMID 34690112, 2021).